CCL2 (C-C motif chemokine ligand 2)
Diseases named in the same sentence as CCL2 in open-access papers (continued):
Sharing a sentence is not in itself a finding about the gene and the disease.
tumor (continued). "Importantly, mRNA levels of Ccr2 and Ccr5, known to be differentially expressed by TAM1 and MDSCs, were enhanced in isolated control tumours compared to liver tissues, postulating an enhanced presence of Ccl2 and Ccl5-responding myeloid cells." (PMID 34830835, 2021). "TAM trafficking into tumours is dependent on CCL2 expression." (PMID 33917287, 2021). "Numerous signaling molecules, including stromal derived factor-1 (SDF-1/CXCL12), transforming growth factor-β (TGF-β), interleukin-8 (IL-8), matrix metalloproteinase-1 (MMP-1), and monocyte chemoattractant protein 1 (MCP-1/CCL2) were shown to be involved in MSC recruitment to the primary tumor site." (PMID 33287630, 2021). "They indicate that properdin expression may promote an immunosuppressive tumour microenvironment in part by increasing the expression of chemoattractants (C5a and CCL2) known to recruit MDSCs and M2 macrophages." (PMID 33494138, 2021). "We, therefore, attempted to examine whether tumor-derived CSF1 or CCL2 was responsible for CXCL7 secretion." (PMID 34789744, 2021). "Depleting or reprogramming TAMs may potentiate effector CTL function and facilitate therapeutic tumor suppression, while MDSCs, Tregs and tumor-derived factors like CCL2 represent potential therapeutic targets." (PMID 34518291, 2021). "However, obese CXCR2 cKO mice had a greater OC-induced ascites accumulation, showing reduced ascitic floating tumor cells and tumor-attached Mo/Mφ with lower triglyceride, free fatty acid, CCL2, and TNF levels compared to obese WT mice." (PMID 34638514, 2021). "Lu et al53 found that CCL2 might accelerate tumour growth by acting as an autocrine or paracrine growth factor." (PMID 34464477, 2021). "Recruitment of inflammatory monocytes/macrophages responding to CCL2 is critical for tumor cell pulmonary seeding.These findings revealed the different mechanisms of metabolic enzyme in regulating the TME and might provide novel targets for cancer therapy." (PMID 34178639, 2021). "Furthermore, it has been found that IL-33 promotes EMT and tumor progression by regulating the expression of CCL2 and recruiting Tregs through the TGF-β signaling pathway in ESCC." (PMID 33390169, 2021). "The results showed that the knockout of tumor-derived CCL2 or host-derived CCL2 could suppress tumor growth and partially diminish the antitumor effect of EE." (PMID 34593796, 2021). "To determine whether NE or EPI directly affect the CCL2 expression, we incubated them in vitro with human liver organoid, mouse tumor cells, mouse-derived BMDMs, and G-MDSCs." (PMID 34593796, 2021). "Some of these cells can upregulate CCL2 expression and participate in tumour progression." (PMID 34464477, 2021). "However, treatment with recombinant human CCL2 (rCCL2) or CCL5 (rCCL5) reversed TAM migration decreased by ILT4-downregulated tumor cells." (PMID 33537094, 2021). "CCL2 is a key chemokine which mediates macrophage recruitment to tumor sites." (PMID 34638388, 2021). "Also, intratumoral RNS production by MDSCs induces CCL2 chemokine nitration and hinders T-cell infiltration, resulting in the trapping of tumor-specific T cells in the stroma that surrounds cancer cells." (PMID 35003065, 2021). "Moreover, PRC1 activity in DNPC leads to the upregulation of CCL2, resulting in bone and visceral metastases, stem cell properties, and the formation of an immunosuppressive tumor microenvironment." (PMID 33921329, 2021). "Besides the primary tumor cell proliferation, we additionally explore the effect of CCL2 in the target organ during the tumor process." (PMID 34249913, 2021). "We then examined expression of CCL2/CCR2 signaling proteins in hDCIS.01 breast lesions." (PMID 33888841, 2021). "Similarly, CD206+/TIE2+ macrophages recruited by tumor-derived CCL2 induced upregulated Wnt-1 and downregulated E-cadherin in early HER2+ tumor cells, establishing a pre-metastatic niche promoting early cancer dissemination and intravasation." (PMID 34884995, 2021).
tumor (continued). "Despite decreased expression of Ccl2 mRNA in CD11b+ cells immunosorted from the tumor-bearing brains of OAT-1746-treated animals, the other cells in the tumor microenvironment could still be the source of the cytokine and augment Ccl2 plasma levels." (PMID 34504786, 2021). "Furthermore, in BM tumors, the increased secretion of CCL2 recruits Iba1+ myeloid cells, which reciprocally enhance BM tumor cell outgrowth via enhanced proliferation and reduced apoptosis." (PMID 34917508, 2021). "Using a lentiviral approach to downregulate the expression of galectin-1 in GL261 glioma cells, the authors found that, 14 days after tumor inoculation, the proportion of TAMs and MDSCs significantly decreased in the TME, and this was associated with lower expression of CCL2 in tumor cells." (PMID 35008740, 2021). "Moreover, the targeted inactivation of IL-6, MCP-1/CCL2 or M-CSF has been shown to augment anti-tumor immunity and reverse resistance to immunotherapy." (PMID 34956864, 2021). "Therefore, increased IDO1 activity facilitates immunosuppression by metabolizing tryptophan and results in deceased effector T cell proliferation and promotes Treg differentiation, and CCL2 recruits MDSCs to the tumor more efficiently." (PMID 35126382, 2021). "The study revealed that the CAF produced the CCL2 chemotactic chemokine which may be involved in the recruitment of immune cells to the tumor microenvironment and in tumor growth regulation." (PMID 33841508, 2021). "CCL2 secreted by stromal cells or tumour cells could recruit inflammatory monocytes to stimulate PMN formation and create a suitable environment for cancer cell colonization." (PMID 34464477, 2021). "GBM cells express high levels of CCL2, which recruits TAMs and promotes tumor growth." (PMID 33766119, 2021). "For LUAD tumor cells with the ability to metastasize to the pleura and foster a malignant pleural effusion (MPE), it has been shown that the determining factor is the presence of KRAS activating mutations, which favor the production of CCL2 by the tumor cells." (PMID 33494181, 2021). "For instance, tumor cell-derived C-C motif chemokine ligand 2 (CCL2) and colony stimulating factor 1 (CSF1) lead to increased infiltration of macrophages in the tumor microenvironment (TME), which, in turn, enhances angiogenesis by inducing vascular endothelial growth factor (VEGF) expression." (PMID 34207286, 2021). "CCL2 has recently been shown to be involved in tumour progression, where the genetic absence of CCL2 inhibited recruitment of splenic myeloid-derived suppressor cells immune cells and reduced tumour growth in a syngeneic model." (PMID 33494138, 2021). "Treatment with anti-CCL2 antibody significantly inhibited the tumor growth of Hepa1-6 in SE mice." (PMID 34593796, 2021). "Nonetheless, the expression of inhibitory and suppressive markers, including genes for IL-4R, IL-10, IL-6, VEGFA, CCL2 and IL-1β, were mostly expressed by cluster 0, suggesting that these cells had a tumor-promoting and immune-suppressing functions, which resemble MDSC-like cells." (PMID 34025646, 2021). "Since we have found the expression of CCL2 could enhance local tumor growth in situ, we next wondered whether the organotropic metastasis regulated by CCL2 is mainly because of the target organ modulation rather than tumor cell proliferation." (PMID 34249913, 2021). "When the p-values are significant, we can reject the null hypothesis and conclude that F. Nucleatum or B. fragilis abundance, together with the presence of tumor, likely influence rates of CCL2." (PMID 34639088, 2021). "Endogenous TRAIL/death receptor-mediated caspase-8 and FADD-dependent inflammatory cytokine (e.g., CCL2/MCP-1) secretion in some TRAIL-resistant cancer cells promotes the accumulation of tumor-supportive immune cells in the cancer microenvironment, thereby encouraging cancer growth." (PMID 33810241, 2021).
tumor (continued). "Inhibition of CCL2 led to a diminution in metastatic seeding, which in some circumstances associated with a decrease in the primary tumor growth, although not necessarily." (PMID 34572013, 2021). "In addition, IL-1β induces the expression of CCL2 in TAMs and tumor cells, leading to the recruitment of myeloid cells such as myeloid derived suppressor cells (MDSCs) and TAMs into the TME." (PMID 34625124, 2021). "However, after the transfection of MMP9‐small interfering RNA(siRNA), MMP9 expression was inhibited and the CCL2‐mediated tumour cell migration was also reduced." (PMID 34464477, 2021). "Blockade of the CCL2/CCR2 pathway could effectively suppress the accumulation of TAMs in experimental tumor sites, and improve efficacy in combination with chemotherapy." (PMID 34248142, 2021). "However, the CCL2/CCR2 axis seems to play a dual role in early tumor immunosurveillance and progression." (PMID 33540898, 2021). "As the level of CCL2/MCP-1 constantly increases during aging, blocking this pathway may alleviate the tumor resistance and improve the ICI efficacy." (PMID 34206425, 2021). "Therefore, neddylation activation promotes the migration of macrophages via regulating tumor/CAF-derived CCL2, indicating synergistic inhibition of neddylation in CCL2-producing cells to target the CCL2-macrophage axis." (PMID 34164400, 2021). "In addition to PF-04136309 and CCX872, Carlumab (CNTO88), a human anti-CCL2 IgG1κ monoclonal antibody (mAb) was evaluated in patients with solid tumors and showed some preliminary anti-tumor activity." (PMID 34771482, 2021). "Previous studies have shown that both stromal‐ and tumour‐derived CCL2 could directly stimulate tumour cell growth and proliferation." (PMID 34464477, 2021). "CCL2 is highly expressed in malignant tumor cells and may play an important role in the recruitment of tumor-associated macrophages." (PMID 34295247, 2021). "Tumor CCL2 and CCL7 increased along with advancing T and CCL3, and CCL4 along with the N stage." (PMID 34885960, 2021). "CCR2 antagonists or knockout of CCL2 in tumor cells significantly reduced metastatic tumor burden." (PMID 34067719, 2021). "Tumor-derived CCL2/MCP-1 produced in tumors in this study ranged from ~10 to 20 pg/ml)." (PMID 34604038, 2021). "CCL2 is overexpressed in tumor cells, including breast, ovarian, and lung cancer." (PMID 33747948, 2021). "Ex vivo primary FL-FDC co-cultures (n = 19) and in vivo mouse co-xenografts demonstrated that FL-FDC crosstalk favors tumor growth and, via the secretion of CCL2 and CSF-1, promotes monocyte recruitment, differentiation, and polarization towards an M2-like protumoral phenotype." (PMID 33731849, 2021). "In addition, NLRP7 promoted the polarization of pro-tumor M2-like macrophages in CRC by inducing the secretion of C-C motif chemokine ligand 2 (CCL2) through the activation of the NF-κB signaling pathway." (PMID 33838681, 2021). "Factors, such as colony-stimulating factor 1 (CSF1) and CCL2, secreted by the TME recruit macrophages to the tumor, and activation of the effector YAP in the Hippo pathway underlies the recruitment of macrophages by tumor-initiating cells (TICs)." (PMID 35071016, 2021). "Moreover, HCC-secreted CCL2 induced PD-L1 expression in tumor-infiltrating neutrophils, which hampered T cell-dependent tumor immunity." (PMID 34386431, 2021). "Moreover, we demonstrated that tumor cell-derived CCL2 was controlled by TCF4 through binding to the promoter region." (PMID 34580284, 2021). "The CCL2/CCR2 pathway contributes significantly to the migration of M-MDSCs to tumor sites." (PMID 34620838, 2021). "Taken together, these data indicated that CCL2 might be the key to EE-induced antitumor immunity and reshaping of the tumor microenvironment." (PMID 34593796, 2021).
tumor (continued). "There is abundant evidence that overexpression of CCL2 promotes tumor metastasis, invasion, and immune resistance; however, some findings indicate that CCL2 expression can also initiate infiltration of anti-tumor inflammatory monocytes." (PMID 34386431, 2021). "Thus, together with direct effects on tumor cells, targeting the CCL2/CCR2 axis likely generates multiple attacks on multiple unfavorable cell types (including cancer cells) within the TME." (PMID 34804061, 2021). "The tumor cells produce CSF-1 and C-C motif chemokine 2 (CCL2) and activate TAMs." (PMID 34281293, 2021). "First, we checked that regardless of the age of the study groups, CCL2 plasma levels were significantly associated with tumor presence (p = 0.00343)." (PMID 34639088, 2021). "Ccl2 and Ccl7 (also known as monocyte chemoattractant protein 1 and 3, respectively) play a critical role in the recruitment of monocytes and neutrophils to the inflamed or tumor tissue, while Ccl17 attracts regulatory T cells." (PMID 34504786, 2021). "In another mouse model of breast cancer, CCL2 secreted by tumor cells could recruit MDSCs to the lung and result in formation of pre-metastatic niche of lung metastases." (PMID 35004667, 2021). "Tumor-derived CCL2 inhibits the efficacy of ablative radiotherapy and FOLFIRINOX chemotherapy in mice, while selective blockade of CCL2 using neutralizing antibodies blocked macrophage recruitment and restored the sensitivity of PDAC tumors to radiotherapy and chemotherapy." (PMID 34201127, 2021). "Furthermore, Curcumin also reduces CCL2‐mediated MMP9 expression that contributes to tumour progression." (PMID 34464477, 2021). "Importantly, the inhibitory effects on tumour growth and the alterations in TME composition caused by USP12 overexpression were efficiently rescued by CXCL1 and CCL2." (PMID 34381028, 2021). "Thus, A3250 cells were highly dependent on TAMs for primary tumor growth, while exaggerated systemic inflammation driven by exceptionally high levels of CCL2 promoted expansion of metastases." (PMID 34824220, 2021). "CCL2 can activate tumour cell growth and proliferation through a variety of mechanisms." (PMID 34464477, 2021). "In addition, the receptors CCR2 and CCR5 were increased in pre-metastatic lung samples, which was probably due to expression on tumor-infiltrated neutrophils, and lung cancer cells were found to secrete their ligands CCL2 and CCL5." (PMID 33105656, 2020). "The mechanism in the resistant tumor model may be mediated by reduced macrophage infiltration, resulting from the suppression of macrophage chemotactic cytokines, C-C motif chemokine ligand 2 (CCL2), expression in tumor cells." (PMID 33233664, 2020). "In addition, CCL2, CCL3, and CCL4 were reported as chemokines associated with worse prognosis and faster tumor progression." (PMID 33238581, 2020). "Also, stroma-derived CCL2/CCL5 induces IL-6 release from the tumor cell generating carboplatin resistance through PYK2 pathway activation (positioned upstream of the JAK1/STAT3 pathway), a critical mediator of survival pathway activation." (PMID 32499779, 2020). "High HOTAIR lncRNA expression promotes the secretion of monocyte chemoattractant protein-1 (MCP-1/CCL2) by tumor cells and promotes the proliferation of tumor-associated macrophages (TAM) and myeloid-derived suppressor cells (MDSC) in the immune microenvironment." (PMID 33391355, 2020). "Notably, inhibition of CCL2 alone or in combination with anti-IL-6 therapy markedly reduced metastases and increased survival of the tumor-bearing animals." (PMID 31811337, 2020). "In the chronically inflamed liver, the accumulation of monocyte-derived macrophages, recruited by CCL2, represents a critical event in the angiogenic and fibrogenic process that may lead to tumor development." (PMID 32784743, 2020).
tumor (continued). "GSEA and additional assays confirmed that ETV5 could promote angiogenesis by inducing the secretion of another tumor angiogenesis factor (CCL2) in CRC cells to facilitate Bevacizumab resistance." (PMID 33099574, 2020). "Several chemokines and their receptors, in particular CCL2 and CCR2, are implicated in PCa progression, metastasis and chemoresistance, and may be expressed by tumour cells or TAMs recruited to the TIME." (PMID 32641865, 2020). "Indeed, we confirmed elevated Ccl2 in a LLC-derived tumor tissue compared with its derived primary cells." (PMID 32244522, 2020). "In summary, the cooperation between tumor-derived chemokines and host/adipose tissue-derived chemokines, particularly CCL2, through CCR2 signaling considerably contributes to tumor cell survival, proliferation, and metastasis, which makes CCR2 a potential therapeutic target in cancer treatment." (PMID 32471499, 2020). "CCL2, a member of the C-C chemokine family, regulates the recruitment of myeloid cells, mostly macrophages and monocytes, into inflamed sites to promote tumor growth." (PMID 32733792, 2020). "In the multivariate Cox’s regression analysis (adjusted for tumor stage and lymph node stage), CCL2-negative patients showed a 2.27-fold increased risk of disease-specific death (p = 0.029)." (PMID 32429318, 2020). "This indicates that the CCL2/CCR2 axis participates in the recruitment of TAMs into tumor tissues." (PMID 33224886, 2020). "CCL2 antibody treatment has proven to suppress tumor metastasis in a breast cancer model." (PMID 33251232, 2020). "CCL2 tumor expression was also observed in a rat astrocytoma model." (PMID 32456359, 2020). "Moreover, CCL2/MCP1 recruit myeloid-derived suppressor cells to the tumor site to alter the microenvironment and promote tumor progression." (PMID 33116117, 2020). "Hence, the CCR2/CCL2 axis has been identified as an interesting target for tumor therapy, and collected data indicate that CCR2/CCL2 signaling plays a relevant role in the tumor-myeloid cell-interaction." (PMID 32668709, 2020). "MDSCs were demonstrated to be recruited to the tumor site by chemokines CCL2, CXCL5, and CXCL12." (PMID 32443699, 2020). "We first report the connection between Wnt5a/CaMKII/ERK/CCL2 axis and biological functions of TAMs in tumor microenvironment, indicating that Wnt5a may be a novel therapeutic target for CRC." (PMID 32140070, 2020). "Such a macrophage polarization was also shown by hypoxic tumor exosomes enriched in CCL2, CSF1, TGF-β, macrophage migration inhibitory factor (MIF), ferritin heavy/light chain, endothelial monocyte-activating polypeptide 2 (EMAP2), and leukotriene A-4 hydrolase." (PMID 32499786, 2020). "Nevertheless, there is a series of results suggesting that the CCL2-dependent signalling pathway could promote the survival of tumor cells and stimulate metastasis and angiogenesis." (PMID 31991604, 2020). "Indeed, it has been demonstrated that PGE2 leads to CCL2 up-regulation, a key chemokine involved in macrophage recruitment in the tumor." (PMID 33271839, 2020). "CCL2 signaling has been shown to accumulate M-MDSCs in multiple tumor models." (PMID 32443699, 2020). "Here, miR‐3473b inhibitor significantly reduced the exosome‐mediated inflammatory genes including Il6, Ccl1, Ccl2, Ccl5 and Cxcl2 expression in fibroblasts, which suggest the potential role of exosomal miR‐3473b in establishing tumour‐promoting inflammation environment." (PMID 32449597, 2020). "Ccl2 has also been reported to increase the cytotoxicity of neutrophils against tumor cells." (PMID 33330473, 2020). "Moreover, protein expression data of three CC chemokines (CCL2/4/27) in tumor and normal tissue were acquired from The Human Protein Atlas, which revealed that the protein expression of CCL2/4/27 was remarkably increased in BC tissues." (PMID 33146700, 2020). "In response to reactive nitrogen species (RNS) tumor cells modify CCL2 intro nitrosylated CCL2." (PMID 33262763, 2020).